ALB (albumin)
Diseases named in the same sentence as ALB in open-access papers (continued):
Sharing a sentence is not in itself a finding about the gene and the disease.
infection (continued). "A greater proportion of patients in the lower albumin group had infection (11.4% vs. 43.8%, p=0.003) and pulmonary complications (5.4% vs, 37.5%, p=0.001) than those in the higher albumin group." (PMID 37082727, 2023). "Lung transvascular albumin flux increased by approximately eightfold, peaked at 6 h post-infection and started to decrease by day 7 post-infection." (PMID 37245027, 2023). "A significantly increased HbA1c/albumin ratio also resulted in significantly increased infection rates." (PMID 37237779, 2023). "PCT to ALB ratio (PAR) is an index calculated as the PCT level divided by the ALB level, which can indicate both the body infection, inflammation, and nutritional status." (PMID 36908271, 2023). "The serum albumin concentration is a common nutritional status indicator that can be influenced by many other factors, such as liver function, inflammation, infection, dehydration and so on." (PMID 36894927, 2023). "A retrospective study of DC patients hospitalized in five third-level hospitals in southwest China showed that six characteristics, including TB, Na, ALB, PTA, WBC count and NLR were important predictors of the risk of infection in patients with DC." (PMID 37704966, 2023). "Our findings of albumin concentration affecting eFA incorporation corroborate virulence pathways by which the bacteria utilize host fatty acids to promote survival during infection and tolerate antibiotic treatments." (PMID 38014966, 2023). "Perioperative RBC transfusion and albumin administration have been reported to be independent predictors of postoperative infection after colorectal surgery." (PMID 36768655, 2023). "Six features, including total bilirubin, blood sodium, albumin, prothrombin activity, white blood cell count, and neutrophils to lymphocytes ratio were selected as predictors for infection in patients with DC." (PMID 37704966, 2023). "Our study revealed that patients with infection and low albumin levels exhibited a decreased proportion of T cell subsets within PBMCs." (PMID 38111573, 2023). "Biomarkers related to the nutritional state (albumin and hemoglobin) or the presence of infection (white blood cell count) are predictors of death in this patient group." (PMID 36831907, 2023). "ALB reduces inflammatory exudation in the lungs and also has antioxidant properties, and serum ALB levels can decrease during oxidative stress or infection, and its antioxidant properties can be impaired, ultimately leading to further tissue damage." (PMID 37685276, 2023). "We identified six candidate features, including TB, Na, ALB, PTA, WBC count and NLR measured at hospital admission, as critical infection risk biomarkers for DC patients." (PMID 37704966, 2023). "Studies have found that during severe infections, ALB decreases while FIB increases due to the cascade reactions of coagulation and inflammation." (PMID 38111666, 2023). "We then categorized ACLF patients based on infection, albumin levels, prothrombin activity, and outcome status." (PMID 38111573, 2023). "As the severity of frailty increases, the proportion of sodium, potassium and albumin supplementation as well as anti-infection gradually increases." (PMID 38249717, 2023). "Cricopharyngeal muscle opening and nutritional (hemoglobin, albumin and prealbumin) and infection (white blood cells and C-reactive protein) indicators were improved in both experimental and control groups, but statistically superior in the former." (PMID 38082316, 2023). "Infection resolved in 94% of patients in the cefotaxime group (94%) and 98% in the albumin group (p = 0.36)." (PMID 37218881, 2023). "Albumin concentrations vary throughout the body and sites of infection and decrease with increasing age, highlighting the importance of understanding the effect of HSA on the utilization of serum fatty acids in S. aureus (18, 44, –, 46)." (PMID 38014966, 2023).
infection (continued). "Our study found that patients with infection and low albumin levels exhibited a decreased proportion of T cell subsets within PBMCs." (PMID 38111573, 2023). "Salivary albumin concentrations were also found in higher concentrations in pigs suffering from infection and/or inflammation." (PMID 37235602, 2023). "A/G ratios were calculated from serum albumin and globulin levels taken prior to infection and necropsy." (PMID 35631065, 2022). "There was a statistically significant association between the modified Glasgow prognostic scoring system (mGPS), C-reactive protein-to-albumin ratio (CAR), neutrophil–platelet score (NPS) and risk of developing a surgical site infection (all p < 0.05)." (PMID 34628535, 2022). "Moreover, albumin has been considered to have antioxidant activity and anti‐inflammatory properties, which may reduce the risk of infection." (PMID 35849734, 2022). "The albumin level in serum is affected by many factors such as inflammation, infection, liver damage, and fluid status." (PMID 36742004, 2022). "The antibody index (AI), a quotient of CSF/serum albumin (Qalb) and immunoglobulin quotients (QIg), is useful to confirm a suspicion of infection in the CNS." (PMID 36419997, 2022). "Several factors such as the use of contraceptives, pregnancy, albumin levels, smoking, ongoing infection, and food have then been shown to influence the serum concentration of zinc and need to be taken into account." (PMID 34967503, 2022). "At day 8 post infection (p.i.), proteinuria was observed with a significant increase in albumin/creatinine ratio in the PbNK65-E infected mice compared to the control mice." (PMID 36004329, 2022). "Restrictive cubic spline regression analysis was also used to examine the relationship between preoperative serum albumin levels and acute postoperative infection." (PMID 36684164, 2022). "The numerical difference value between HCT (%) and ALB (g/L) levels (HCT-ALB) is highly sensitive and specific among patients with infectious diseases and is, therefore, a potential indicator for the differential diagnosis of infections." (PMID 35850582, 2022). "It is common for patients with TB not to be diagnosed and treated until months after developing active infection;23 the patients enrolled in these clinical trials had signs and symptoms of chronic infection, including low BMI and low serum albumin levels." (PMID 35650700, 2022). "In some studies, plant extracts were reported to reduce serum GLB and increase ALB and A:G in infection-free broiler chickens." (PMID 35544959, 2022). "This study analyzed the role of pre-operative albumin and white blood cell count, among other covariates, in predicting the occurrence of surgical site infection after Whipple surgery using the General Surgery NSQIP dataset from 2011 through 2017." (PMID 36357432, 2022). "Laboratory investigations before shunt surgery were studied within six months, including complete blood count (hemoglobin, white blood cells, platelets), random serum glucose, and albumin, to detect any correlation with developing complications or infection." (PMID 36060349, 2022). "Cheong Wei Eu found that a decrease in serum albumin levels (<35 g/L) results in an increased rate of postoperative surgical site infection." (PMID 36558490, 2022). "Hypoalbuminemia indicates the severity of inflammation and can be an additional risk stratification biomarker for mortality and prognosis, with an acute drop in serum albumin levels immediately after infection predicting a poor prognosis." (PMID 36407534, 2022). "Creatinine clearance, serum albumin concentrations, and location of infection were similar for patients receiving meropenem and piperacillin/tazobactam." (PMID 35740164, 2022). "In fact, visceral proteins, such as pre-albumin, also reflect the dynamic and catabolic response to surgery, stress, injury, infection, and organ dysfunction." (PMID 35276795, 2022).
infection (continued). "Overall, the resolution of infection was resolved in 94.69% patients in the albumin group and in 97.34% in the control group." (PMID 36721617, 2022). "We examined the dose-response relationship between preoperative serum albumin levels and acute postoperative infection by using restrictive cubic spline regression analysis." (PMID 36684164, 2022). "Other biomarkers such as C-reactive protein (CRP), erythrocyte sediment rate (ESR) procalcitonin and CRP/albumin ratio have been reported as useful predictors of postoperative infection." (PMID 35246692, 2022). "Despite this abundancy, albumin had negligible effects on signal production following phage reporter infection." (PMID 36016370, 2022). "In our analysis, it also took 2–3 months for serum albumin to return to the baseline values seen in the months before infection." (PMID 34378318, 2022). "Of the other covariates, older age, low levels of hemoglobin, albumin, creatinine, the higher half of IL-6, and a past history of CVD were also associated with the risk of infection-related hospitalization in the univariate Cox proportional hazards model." (PMID 35155493, 2022). "Serum albumin shown to play a critical role inP. aeruginosa virulence during early phases of infection by enhancing the expression of iron-controlled genes." (PMID 36519007, 2022). "Second, a U-shaped relationship between albumin-corrected calcium level and 30-day in- hospital mortality was discovered in our study, and we also calculated the infection point at the same time." (PMID 36619536, 2022). "The sample size was based on our feasibility study, and samples were selected by a trial statistician stratified by the serum albumin level and the presence of infection at randomization and analyses performed blinded to the study arm." (PMID 35333783, 2022). "Conversely, treatment with COX inhibitors or albumin restored immune competence and survival following infection with group B Streptococcus." (PMID 35432367, 2022). "Collectively, both decreased albumin and increased globulin played essential roles in response to inflammation and infection functions to dramatically decrease the AGR, suggesting that AGR indicates the body’s inflammatory state more accurately." (PMID 36309703, 2022). "The most likely reason for this is that the level of albumin is likely to be affected by nutritional status and also by inflammation and infection, which restricts its application as a detection marker for critically ill patients." (PMID 35755035, 2022). "Albumin, which is synthesized by the liver, is the main serum protein component of the human body, which maintains osmotic pressure and resists infection and oxidation." (PMID 35401217, 2022). "ALB plays a crucial role in immunomodulation during chronic liver disease processes, and albumin is negatively correlated with infection in patients with chronic liver diseases." (PMID 35655296, 2022). "Serum albumin levels, an easily available biomarker, have been proven to be related to postoperative infections." (PMID 35497986, 2022). "Only albumin of the APPs decreased in effect size in both moderate and severe cases of infection and in diseased relative to control comparisons." (PMID 35902827, 2022). "The patient received symptomatic and supportive treatment of anti-infection and albumin supplementation." (PMID 35783634, 2022). "E5 viral RNA (vRNA)-positive cells colocalized exclusively with albumin, identifying hepatocytes as the main cellular target of infection in the liver following dissemination from the GI tract." (PMID 35604122, 2022). "A low PWR was correlated with older age, a higher hemoglobin level, higher ALT level, lower albumin level, increased CRP level and infections with unidentified causative pathogens." (PMID 36292245, 2022).
infection (continued). "Preoperative serum albumin value is a formidable predictor of postoperative surgical site infections, wound dehiscence, and duration of hospital stay in patients who underwent emergency exploratory laparotomy." (PMID 36589182, 2022). "Two studies compared the overall events of the resolution of infection between patients in the albumin group and control group." (PMID 36721617, 2022). "A recent report on inflammatory biomarkers in patients with BSI demonstrated that lower albumin levels in neutropenic BSI indicate a poorer infection prognosis." (PMID 35559342, 2022). "For example, human serum albumin can bind C. difficile TcdA and TcdB toxins, reduced bacterial toxin dependent infection, and helped protect the host cell." (PMID 35873567, 2022). "It is well known the increased risk of infections with these mAbs, and a score including age, LDH, albumin, and ALT at baseline has been also built to identify patients at higher risk of infections when they receive anti-CD38 mAbs." (PMID 35440057, 2022). "The calculated critical levels of NEU, WBC, CRP, Urea, Albumin, and Calcium features are important levels in determining the severity of infection of the patients." (PMID 35808317, 2022). "Low albumin, history of a tracheostomy, and long-term use of antibiotics were independent risk factors for MRDO infection and are worthy of attention." (PMID 35773340, 2022). "Four subject-specific factors were found to be predictive of the variability in rezafungin PK: BSA, infection status, serum albumin, and sex." (PMID 34398673, 2021). "The infection of MRSA caused an increase in uric acid and decreases in alkaline phosphatase, albumin, glycosylated serum protein, and triglyceride." (PMID 34439068, 2021). "SPEPs in a blood parasite single infection mostly showed decreased albumin levels and A/G ratios and increased β2- and γ-globulin levels." (PMID 34566333, 2021). "All 24 patients with CNS received nutritional support, diuretics, albumin infusion, preventive measures, treatment of infection, and other symptomatic support treatment at disease onset." (PMID 34859019, 2021). "A recent cohort of 1,000 patients in CKD patients reported that increased albumin-creatinine ratios and reduced glomerular filtration rate (GFR) were associated with higher infection rate, severity, increased risk of hospitalization, and mortality." (PMID 33959457, 2021). "Decreased albumin (< 35 g/L) has been identified as an independent predictor of severe infection requiring intensive care unit (ICU) admission in MERS infection." (PMID 34238232, 2021). "ALB was more effective in achieving sustained clearance of STH infection in subjects with light baseline infection intensities compared to those with higher egg counts." (PMID 34103096, 2021). "Pain management, antibiotic and anthelmintic therapy, fluid therapy, human albumin, force feeding, and wound debridement were provided to manage the shell fractures and to control the infection." (PMID 34944256, 2021). "Compared to the control infection conditions, colonization with L. rhamnosus, prevented the increased epithelial damage in the presence of albumin, similarly to how L. rhamnosus prevents damage induced by the highly pathogenic species C. albicans." (PMID 34710198, 2021). "Further studies are required to determine the role of albumin supplementation as coadjutant treatment in a such critical infection." (PMID 34768653, 2021). "The control of infection was indicated clinically by a gradual reduction of constitutional symptoms, bacterial colony count, and improvement of serum albumin and electrolytes." (PMID 33833953, 2021). "Considering the ubiquitous presence of albumin, we investigated its role in the pathogenesis of infections with the model human fungal pathogen, Candida albicans." (PMID 34154403, 2021).
infection (continued). "In dogs infected with E. canis, B. canis, and H. canis single infections, albumin levels and A/G ratios significantly decreased, whereas β2-globulin levels increased (p<0.05)." (PMID 34566333, 2021). "Clinical chemistries noted significant increases in globulin and glucose and decreases in albumin and the albumin:globulin ratio (A/G) during lethal infection." (PMID 33534855, 2021). "After admission, the patient received anti-infection and symptomatic treatment including repeated albumin for protein supplementation and repeated acid correction." (PMID 35111204, 2021). "Variables that were significantly different between groups include serum sodium, creatinine, PT/INR, albumin, and diagnosis of infection (defined in Appendix A)." (PMID 34201606, 2021). "To elucidate how the pathogenic potential of C. glabrata is modified in the presence of albumin, we performed transcriptional profiling of C. glabrata at different time points during infection." (PMID 34710198, 2021). "As such, our work identifies a novel mechanism by which albumin can modulate infection, potentially identifying albumin as an important player in defense against microbial toxins." (PMID 34154403, 2021). "We previously reported that accumulation of oxidized serum albumin triggers infection-independent NETotic cell death by intracellular accumulation of reactive oxygen species (ROS), which contributes to the promotion of pulmonary cancer metastasis." (PMID 33933883, 2021). "No drastic differences in fungal morphology were observed during the infection of kidney cells in the presence of albumin." (PMID 34154403, 2021). "It is mainly synthetized in the liver, and during the parenchymal stage of infection, liver damage produced by the migrating parasites leads to a decrease in albumin production." (PMID 34122452, 2021). "As a strong marker in diseases related to infection and inflammation, the ALB level usually decreases during the acute period." (PMID 34733230, 2021). "The reduction of albumin levels can lead to a series of adverse effect, such as reducing anti-infection ability, weakening respiratory muscles, decreasing ventilation function, declining lung function." (PMID 34861893, 2021). "As for prealbumin, another widely used serum marker of nutritional status characterized by a much shorter half lifetime than that of albumin, its specificity is also limited when infection or inflammation are present." (PMID 34835927, 2021). "Increased glucose availability during infection rescued epithelial cell survival in the presence of albumin." (PMID 34710198, 2021). "Collectively, these results strongly suggest that albumin needs to be present during infection in order to prevent C. albicans-induced damage to host cells." (PMID 34154403, 2021). "Univariate analysis indicated that age, WBC count, Hb, PLT, AST, ALB, TBil, INR, Na, Cr, AFP, HBeAg, HBV DNA, HRS, GB, HE, infection, and PreLD were associated with 90-day transplantation-free survival." (PMID 34222294, 2021). "The level of albumin was negatively correlated with infection prognosis in all patients (P = 0.03), and negatively correlated with neutrophil count and CRP (P = 0.008, P < 0.001)." (PMID 34712677, 2021). "Trans-capillary leakage of serum albumin correlates with infection severity and increases interstitial levels of albumin." (PMID 33925831, 2021). "Li Wq pointed out that the distribution rate of serum albumin from intravascular to extravascular increases significantly during an infection, and the decomposition rate of albumin also increases significantly." (PMID 35174183, 2021). "Before infection, seventy days after initiating the experimental diet, both the uninfected and infected LP 3% groups showed a significant reduction in the albumin concentration in relation to mice fed with the control diets." (PMID 33815321, 2021).